SFRP2 (secreted frizzled related protein 2)
Description:
Soluble frizzled-related proteins (sFRPS) function as modulators of Wnt signaling through direct interaction with Wnts. They have a role in regulating cell growth and differentiation in specific cell types. SFRP2 may be important for eye retinal development and for myogenesis.
Synonyms: FRP-2; SARP1; SDF-5
Tractability: Antibody: UniProt places it where antibodies can reach, with medium confidence; UniProt predicts a signal peptide or a membrane-spanning region; its Gene Ontology location is reachable by antibodies, with medium confidence.
Gene: Protein-coding gene on chromosome 4 (153,780,591 to 153,789,083, reverse strand). Ensembl gene ENSG00000145423.
Subcellular location: Secreted
Subcellular location (Human Protein Atlas): Intermediate filaments; Predicted to be secreted
Pathways (Reactome):
Signal Transduction: Negative regulation of TCF-dependent signaling by WNT ligand antagonists; TCF dependent signaling in response to WNT
Gene Ontology:
Molecular function: fibronectin binding; integrin binding; receptor ligand activity; Wnt-protein binding; endopeptidase activator activity; enzyme activator activity
Biological process: cardiac left ventricle morphogenesis; negative regulation of canonical Wnt signaling pathway; negative regulation of cell growth; negative regulation of cell population proliferation; negative regulation of DNA-templated transcription; negative regulation of epithelial cell proliferation; negative regulation of epithelial to mesenchymal transition; negative regulation of Wnt signaling pathway; outflow tract morphogenesis; positive regulation of apoptotic process; positive regulation of cell population proliferation; positive regulation of fat cell differentiation; branching involved in blood vessel morphogenesis; canonical Wnt signaling pathway; cell-cell signaling; hematopoietic stem cell proliferation; negative regulation of cell migration; negative regulation of dermatome development; negative regulation of gene expression; negative regulation of intrinsic apoptotic signaling pathway in response to DNA damage; negative regulation of peptidyl-tyrosine phosphorylation; non-canonical Wnt signaling pathway; positive regulation of angiogenesis; positive regulation of canonical Wnt signaling pathway; positive regulation of cell adhesion mediated by integrin; and 13 more
Cellular component: extracellular region; extracellular matrix
Genetic constraint (gnomAD): Loss-of-function variants: 13 observed, 23.38 expected, observed/expected ratio (o/e) 0.56, 90% interval 0.36 to 0.88. The upper end of that interval is the gene's LOEUF score, 0.88, which puts it in group 3 of 6, group 1 being the genes least tolerant of losing a copy. Missense variants: 311 observed, 377.13 expected, observed/expected ratio (o/e) 0.82, 90% interval 0.75 to 0.91. Synonymous variants: 161 observed, 160.75 expected, observed/expected ratio (o/e) 1, 90% interval 0.88 to 1.14.
Homologues: Orthologues: chimpanzee SFRP2 (100% identical), macaque SFRP2 (99% identical), pig SFRP2 (98% identical), rabbit SFRP2 (98% identical), dog SFRP2 (98% identical), mouse Sfrp2 (98% identical), rat Sfrp2 (98% identical), guinea pig SFRP2 (97% identical), tropical clawed frog sfrp2 (82% identical), zebrafish sfrp2 (71% identical), Drosophila melanogaster fz3 (20% identical). Paralogues in human: SFRP1 (41% identical), SFRP5 (40% identical), FZD2 (29% identical), FZD7 (29% identical), FZD1 (28% identical), FZD10 (28% identical), FZD8 (28% identical), FZD5 (27% identical), FZD9 (27% identical), FZD4 (25% identical), FZD3 (25% identical), FZD6 (24% identical), and 3 more.
Diseases named in the same sentence as SFRP2 in open-access papers:
SFRP2 is named in the same sentence as 166 diseases in open-access papers, as found by Europe PMC text mining. Sharing a sentence is not in itself a finding about the gene and the disease. The quoted sentences say what the papers report.
breast carcinoma (45 papers, 2006 to 2026). "Overall, our data demonstrated that serum sFRP2 shows a similar diagnostic performance for breast cancer patients compared to conventional biomarkers." (PMID 30944668, 2019). "Sfrp2 (“secreted frizzled-related protein”) is a cell surface protein that is highly expressed by breast cancer-associated endothelial cells and correlates inversely with survival." (PMID 31299925, 2019). "Recently, a few groups have independently reported that sFRP2 is highly expressed in breast cancer and associated with tumor progression, which led us to evaluate serum sFRP2 as a biomarker for breast cancer diagnosis." (PMID 30944668, 2019). "Kaplan-Meier and Cox regression analysis also found that elevated sFRP2 level was associated with a poor prognosis and can be an independent prognostic factor for breast cancer patients." (PMID 30944668, 2019). "This showed that serum sFRP2 was elevated in breast cancer patients, and it was associated with the disease progression of cancer." (PMID 30944668, 2019). "Invasive breast carcinomas showed strongly reduced or complete loss (IRS ≤ 4) of SFRP2 expression in 74% (93/125) of cases." (PMID 18990230, 2008). "Our study reveals a common SFRP2 protein loss in human breast carcinomas with comparable frequency to promoter methylation, notably by applying the identical SFRP2-antibody that was used for the study of canine mammary tumors." (PMID 18990230, 2008). "In summary, our data confirm that the SFRP2 gene is high-frequently inactivated by promoter methylation in human breast cancer and that loss of SFRP2 expression confers a growth advantage to mammary epithelial cells." (PMID 18990230, 2008). "Furthermore, the decreased expression of SFRP2 is associated with the poor prognosis of breast cancer patients, and its tumor suppressor function in breast cancer has been supported." (PMID 41280939, 2025). "Additionally, SFRP2 overexpression has been associated with increased tumor size and reduced survival rates in breast cancer and among prostate cancer patients who experienced BCR." (PMID 37965470, 2023). "Moreover, elevated serum levels of SFRP2 are associated with poor prognosis and metastasis in breast cancer patients, in which the SFRP2 promoter is, similar to prostate cancer, hypermethylated in the primary cancer side." (PMID 36552843, 2022). "In addition, SFRP2 is also upregulated and associated with poor prognosis of breast cancer and colorectal cancer." (PMID 34852024, 2021). "Specifically, SFRP2 hypermethylation (and consequent loss of SFRP2 expression) has widely been documented in several cancer types, such as gastric cancer, osteosarcoma, and breast cancer." (PMID 32517740, 2020). "Because serum sFRP2 can be conveniently measured by the application of a commercial ELISA kit, our initial results demonstrate the potential value of sFRP2 as a diagnostic biomarker for breast cancer." (PMID 30944668, 2019). "This suggested that serum sFRP2 is a potential diagnostic biomarker for breast cancer." (PMID 30944668, 2019). "As a secreted protein, serum sFRP2 could be a diagnostic biomarker in certain type of cancers; however, little is known about serum sFRP2 in breast cancer." (PMID 30944668, 2019). "In this study, to explore the diagnostic and prognostic value of serum sFRP2 in breast cancer, we examined serum levels in breast cancer patients by enzyme-linked immunosorbent assay (ELISA) and assessed the association between serum sFRP2 and clinicopathological features." (PMID 30944668, 2019). "Here we investigated whether SFRP2 is also implicated in human breast cancer, and if so whether SFRP2 promoter methylation might serve as a potential tumor biomarker." (PMID 18990230, 2008). "SFRP2 methylation may be implicated in such field defect in breast cancer, yet dense methylation of the SFRP2 promoter was restricted to carcinoma in our study, and thus it may display important clinical specificity." (PMID 18990230, 2008).
breast carcinoma (continued). "In breast cancer, high-frequency methylation of the promoter of the SFRP2 gene leads to its expression silencing." (PMID 41280939, 2025). "PCK1, LPL, and SFRP2 play a role in breast cancer’s initial and developmental stages, and KRT6B is exclusively related to the developmental stages." (PMID 38791477, 2024). "Our studies demonstrated a decrease in stromal SFRP1 and SFRP2 expression in breast cancer stroma, with the lowest levels observed in IDC tissues." (PMID 37091166, 2023). "Several studies reported that SFRP2 serves as a biomarker for breast cancer, in addition to various other cancers." (PMID 38069266, 2023). "Serum SFRP2 was found to be elevated in patients with breast cancer compared to a control group and was an independent prognostic predictor of progression-free survival." (PMID 34070758, 2021). "Switching to another approach, treatment of angiosarcoma or breast cancer, using an anti-SFRP2 antibody, results in a significant tumor growth inhibition." (PMID 33140138, 2021). "Similar pro-metastatic effects of SFRP2 were also observed for breast cancer cells and melanoma cells." (PMID 33140138, 2021). "When investigating the levels of SFRP2 in serum of breast cancer patients, levels were found to be elevated in patients, as compared to controls." (PMID 33140138, 2021). "A humanised SFRP2 monoclonal antibody has been demonstrated to reduce angiosarcoma and breast cancer growth in mice models." (PMID 33670920, 2021). "We first measured the serum sFRP2 concentration using an ELISA kit in 274 breast cancer patients and 147 normal healthy controls." (PMID 30944668, 2019). "In contrast, the expression of sFRP2 is upregulated in renal cancer and breast cancer, resulting in canonical Wnt signaling activation and tumorigenesis." (PMID 30944668, 2019). "We then evaluated the diagnosis ability of sFRP2 for breast cancer, and serum sFRP2 displayed significantly higher sensitivity than CEA and CA15.3, with slightly lower specificity." (PMID 30944668, 2019). "In conclusion, serum sFRP2 can act as a noninvasive biomarker with high sensitivity for diagnosis and prognosis of breast cancer." (PMID 30944668, 2019). "Serum sFRP2 concentrations were detected in 274 breast cancer patients along with 147 normal healthy controls by enzyme-linked immunosorbent assay (ELISA)." (PMID 30944668, 2019). "In this study, we found that serum sFRP2 concentrations were increased in breast cancer patients compared with normal healthy controls." (PMID 30944668, 2019). "Previous studies of SFRP2 only indicate that this gene is overexpressed in the vascular system of 85% of patients with breast cancer." (PMID 30834271, 2019). "We also found that elevated serum sFRP2 concentrations accompanied poor progression-free survival in breast cancer patients." (PMID 30944668, 2019). "The mean serum concentration of sFRP2 in breast cancer patients was 58.8 ± 18.2 ng/mL, which was obviously higher than the mean serum sFRP2 level in normal healthy controls (mean 34.9 ± 15.5 ng/mL, P < 0.001)." (PMID 30944668, 2019). "Then, we analyzed the relationship between serum sFRP2 and clinicopathological characteristics of breast cancer patients." (PMID 30944668, 2019). "sFRP2 has recently been found to drive tumorigenesis, tumor metastasis, and drug resistance in several cancers, including melanoma, renal cancer, and breast cancer." (PMID 30944668, 2019). "sFRP2 mAb treatment of angiosarcoma allografts or MDA-MB-231 breast carcinoma xenografts in nude mice significantly reduced tumors volume." (PMID 26056595, 2014). "For example, sFRP2 is over-expressed in human angiosarcoma and breast cancer and stimulates angiogenesis via activation of the calcineurin/NFATc3 pathway." (PMID 26056595, 2014). "We showed here that Wnt5a activated Dvl2, Daam1 and RhoA, and promoted migration of breast cancer cells, which was, however, abolished by Secreted Frizzled-related protein 2 (sFRP2) pretreatment." (PMID 22655072, 2012).
breast carcinoma (continued). "Recent work has identified a novel angiogenesis factor, secreted frizzled-related protein 2 (SFRP2), which is expressed in the vasculature of a wide variety of tumors including human breast carcinoma." (PMID 21673995, 2011). "This demonstrates that NFATc3 is required for SFRP2 induced tube formation, and tacrolimus inhibits angiogenesis in vitro and breast carcinoma growth in vivo." (PMID 21673995, 2011). "We here demonstrate that promoter methylation of SFRP2 is a further tumor-related alteration in human breast cancer occurring with even higher incidence." (PMID 18990230, 2008). "Our study on SFRP2 in human breast cancer leads to the following conclusions: SFRP2 expression is very frequently downregulated in breast cancer due to promoter methylation, thus conferring growth advantage to neoplastic mammary cells." (PMID 18990230, 2008). "To further confirm that SFRP2 promoter methylation in breast cancer is restricted to malignant tissue, we analyzed 17 cancer-unrelated normal breast samples." (PMID 18990230, 2008). "Summarizing, our data demonstrate that SFRP2 is a frequent target of epigenetic inactivation in human breast cancer leading to downregulation of SFRP2 expression in mammary tumors." (PMID 18990230, 2008). "A direct coherence between promoter methylation and loss of RNA expression was shown by a combined DAC/TSA treatment of breast cancer cell lines, demonstrating that the SFRP2 gene was effectively demethylated and re-expressed after the treatment." (PMID 18990230, 2008). "SFRP2 methylation was equally prevalent in small sized (pT1) and in larger sized (pT2-4) breast carcinomas, suggesting it occurs as early epigenetic aberration in breast tumorigenesis with no further increase in methylation frequency during tumor progression." (PMID 18990230, 2008). "Clinicopathological characteristics of breast cancer patients were first correlated with SFRP2 protein expression for descriptive data analysis." (PMID 18990230, 2008). "SFRP2 expression was substantially restored in most breast cell lines after treatment with 5-aza-2'-deoxycytidine and trichostatin A. In primary breast carcinomas SFRP2 protein expression was strongly reduced in 93 of 125 specimens (74%)." (PMID 18990230, 2008). "The genes include members of the family of secreted frizzled-related proteins (SFRP1 and SFRP2), which are frequently epigenetically inactivated during colon and breast cancer progression, and contribute to aberrant activation of Wnt signaling." (PMID 16596166, 2006). "Promoter hypermethylation led to the abrogation of sFRP2 in breast cancer." (PMID 39076470, 2024). "However, further research is needed to analyze the mechanism of the genes SHC2, KRT6B, and SFRP2 in breast cancer liver metastasis." (PMID 38791477, 2024). "SFRP2, a protein in the SFRP family, was found to act as a counter-direction signal from the Wnt/β type pathway, and is associated with various cancer incidences, including breast cancer." (PMID 38791477, 2024). "As such, SFRP1 and SFRP2 expression in fibroblasts could serve to regulate breast cancer progression by acting on epithelial cells and other cells in the tumor microenvironment." (PMID 37091166, 2023). "What is the potential significance of stromal SFRP1 and SFRP2 expression in breast cancer?" (PMID 37091166, 2023). "After cancer cells enter the circulation to metastasize, osteotropic activity of prostate cancer cells could be detected by elevated serum SFRP2 levels in patients, similar to breast cancer patients with a poor prognosis." (PMID 36552843, 2022). "In brain tumors, breast cancer, ovarian cancer, gastric cancer, and esophageal cancer, the SFRP2 promoter is hypermethylated, suggesting SFRP2 may act as a tumor suppressor." (PMID 36091174, 2022). "SFRP2 is hypermethylated and silenced in a subset of breast cancers and experiments in model systems have shown cross-talk between ER and Wnt signaling that may mediate endocrine therapy resistance." (PMID 33407744, 2021).
breast carcinoma (continued). "Interestingly, SFRP2 is described to be overexpressed in the tumor vasculature of breast cancer tissues." (PMID 33140138, 2021). "Serum SFRP2 has previously been shown to be a predictive biomarker for patients with breast cancer." (PMID 34070758, 2021). "So, in the context of breast cancer, SFRP2 levels in serum may be a promising biomarker and prognostic prediction tool." (PMID 33140138, 2021). "Similarly, lung alveolar epithelial cells have been reported to induce Src-mediated Secreted frizzled-related protein 2 (SFRP2) in breast cancer cells promoting FN1 fibril formation and cancer cell survival." (PMID 33731188, 2021). "And while one study reported SFRP2 promoter hypermethylation in more than 80% of breast cancer patients, a recent report suggests that, in contrast, elevated serum levels of SFRP2 may serve as an independent marker for poor prognosis." (PMID 32083079, 2020). "We evaluated serum sFRP2 as a potential biomarker for breast cancer." (PMID 30944668, 2019). "The breast cancer patients' median concentration of serum sFRP2 (58 ng/mL) was categorized as a threshold to divide the 274 breast cancer patients into two groups: a high serum sFRP2 group (>58 ng/mL, n = 129) and a low serum sFRP2 group (≤58 ng/mL, n = 145)." (PMID 30944668, 2019). "Furthermore, ROC analysis showed that serum sFRP2 had the potential to distinguish breast cancer patients from normal healthy controls with high sensitivity." (PMID 30944668, 2019). "In conclusion, serum sFRP2 may serve as a potential biomarker for breast cancer diagnosis and prognostic evaluation." (PMID 30944668, 2019). "Serum sFRP2 was elevated in breast cancer patients compared to normal healthy controls (P < 0.001)." (PMID 30944668, 2019). "Second, six genes, CHI3L1, CXCL8, FOXC2, SERPINE1, SFRP2, and TF, which are grouped within the highest enrichment GO term, “positive regulation of angiogenesis”, have been reported to play roles in various cancer processes, including breast cancer." (PMID 30205506, 2018). "Furthermore, single cell RNA-sequencing in breast cancer suggests that SFRP2 and SFRP4 expression is restricted to cells identified as stromal." (PMID 28218291, 2017). "However, recently reports provide evidence that sFRP2 can enhance tumor aggressiveness or progression in several cancers, including melanoma, renal cancer, angiosarcoma, and breast cancer." (PMID 27821163, 2016). "However, overexpression of sFRP2 has been reported in renal cancer, human angiosarcoma, and breast cancer, which leads to angiogenesis stimulation by activation of the calcineurin/NFATc3 pathway." (PMID 27821163, 2016). "Since both VEGF and SFRP2 are expressed in breast carcinomas, we hypothesized that tacrolimus would inhibit breast carcinoma growth." (PMID 21673995, 2011). "Indeed, sFRP1 has also been shown to impact on transforming properties of breast cancer cells and cervix cancer cells; while sFRP2 has been shown to block proliferation of gastric cancer cells." (PMID 19473496, 2009). "In contrast to an adverse prognostic value of SFRP1 or SFRP5 methylation in breast cancer, failure of SFRP2 methylation as a prognostic biomarker may be explained by redundant functions of these closely related SFRP molecules." (PMID 18990230, 2008). "The SFRP2 gene is a high-frequent target of epigenetic inactivation in human breast cancer." (PMID 18990230, 2008). "We analyzed SFRP2 mRNA expression and SFRP2 promoter methylation in 10 breast cell lines, 199 primary breast carcinomas, 20 matched normal breast tissues and 17 cancer-unrelated normal breast tissues using RT-PCR, realtime PCR, methylation-specific PCR and Pyrosequencing, respectively." (PMID 18990230, 2008). "To this end we analyzed SFRP2 promoter methylation in 199 infiltrating breast carcinomas by MSP." (PMID 18990230, 2008).